LRRC40 (leucine rich repeat containing 40)
Synonyms: FLJ20331; dJ677H15.1
Tractability: PROTAC: ubiquitination databases record sites on it; its protein half-life has been measured.
Gene: Protein-coding gene on chromosome 1 (70,143,411 to 70,205,639, reverse strand). Ensembl gene ENSG00000066557.
Subcellular location (Human Protein Atlas): Nucleoli
Gene Ontology:
Molecular function: protein binding
Biological process: intracellular signal transduction
Cellular component: membrane
Genetic constraint (gnomAD): Loss-of-function variants: 20 observed, 19.99 expected, observed/expected ratio (o/e) 1, 90% interval 0.7 to 1.45. The upper end of that interval is the gene's LOEUF score, 1.45, which puts it in group 6 of 6, group 1 being the genes least tolerant of losing a copy. Missense variants: 240 observed, 241.54 expected, observed/expected ratio (o/e) 0.99, 90% interval 0.89 to 1.11. Synonymous variants: 89 observed, 89.99 expected, observed/expected ratio (o/e) 0.99, 90% interval 0.83 to 1.18.
Homologues: Orthologues: chimpanzee LRRC40 (99% identical), macaque LRRC40 (98% identical), dog LRRC40 (89% identical), rabbit LRRC40 (89% identical), mouse Lrrc40 (83% identical), guinea pig LRRC40 (82% identical), rat Lrrc40 (82% identical), zebrafish lrrc40 (63% identical), tropical clawed frog lrrc40 (63% identical). Paralogues in human: ERBIN (25% identical), SCRIB (24% identical), LRRC7 (24% identical), PHLPP1 (23% identical), SHOC2 (23% identical), LRRD1 (22% identical), PHLPP2 (22% identical), PIDD1 (22% identical), LRRC1 (20% identical), MFHAS1 (20% identical), LRRIQ4 (20% identical), LRRC8D (19% identical), and 19 more.
Diseases named in the same sentence as LRRC40 in open-access papers:
LRRC40 is named in the same sentence as 5 diseases in open-access papers, as found by Europe PMC text mining. Sharing a sentence is not in itself a finding about the gene and the disease. The quoted sentences say what the papers report.
cancer (1 paper, 2022). A tumor composed of atypical neoplastic, often pleomorphic cells that invade other tissues. "TK1 has long been used as a diagnostic and prognostic marker in AML, and PCMTD2 and LRRC40 have been used as diagnostic or prognostic markers in other types of cancer." (PMID 35656299, 2022).
LRRC40 also shares sentences with these, for which no sentence is quoted: cervical cancer (1 paper); epilepsy (1); glycogenosis (1); Wilms tumor (1).